EZH2 (enhancer of zeste 2 polycomb repressive complex 2 subunit)
Diseases named in the same sentence as EZH2 in open-access papers (continued):
Sharing a sentence is not in itself a finding about the gene and the disease.
tumor (continued). "Stage-specific analysis further identified key drivers of distinct disease transitions including EZH2 and PLK1 as major regulators of androgen dependence in mHSPC, and TERT as a hallmark of mCRPC, highlighting its role in telomere maintenance and tumor progression." (PMID 41402347, 2025). "The high expression of DNMT1 in tumor cells was previously linked to the binding of MYC to the DNMT1 promoter region and subsequent activation of its transcription, where DNMT1 can be further recruited by enhancer of EZH2 to methylate the promoter sequence of tumor suppressors." (PMID 40317882, 2025). "However, when HCC patients were stratified by tumor grade, a significant decrease in EZH2 promoter methylation was observed in advanced-stage tumors." (PMID 41209556, 2025). "Notably, treatment with an EZH2 inhibitor restores immune cell infiltration and inhibits tumor growth in NSD1-mutant models, highlighting a druggable chromatin crosstalk with potential therapeutic relevance." (PMID 40586874, 2025). "Additionally, studies have shown that combining enzalutamide with the enhancer of zeste homolog 2 (EZH2) inhibitor GSK-126 remodels the tumor immune microenvironment by activating CD8+ T cells and IFN-γ production." (PMID 41079787, 2025). "We hypothesized that EZH2 inhibition in TNBC cells per se would exert antitumor activity by altering the tumor immune microenvironment." (PMID 38791429, 2024). "Moreover, FBXW7 suppresses tumor aggressiveness by degrading other substrates, such as Enhancer of zeste homolog 2 (EZH2)." (PMID 39749199, 2024). "Surprisingly, treatment with an anti-CCL2 antibody of KPC tumors treated with MEK and CDK4/6 inhibitors, along with an EZH2 blockade, led to a significant reduction in anti-tumor effects, highlighting that NK cell accumulation was critical for tumor regression." (PMID 38339310, 2024). "Blocking EZH2 in orthotopic, murine, KPC tumors, treated with MEK and CDK4/6 inhibitors, subsequently led to an increase in intra-tumoral CCL2 and CXCL9/10 production and was associated with NK- and T-cell influx and anti-tumor responses." (PMID 38339310, 2024). "To study the effects of EZH2 inhibition in combination with immunotherapy in vivo, we induced tumors to grow in the lungs in Lkb1/Pten mice by adeno-Cre inhalation and after 40–50 weeks, we randomized tumor-bearing mice onto four treatment arms." (PMID 38265267, 2024). "In support of this, an increase in the histone methyltransferase, EZH2, in metastatic SCC compared to non‐metastatic tumours was associated with an impairment in innate immunity that enabled the escape of tumour cells from the immunosurveillance system to result in metastases." (PMID 39624739, 2024). "However, inhibiting EZH2 in vivo was promising, leading to several studies focusing on the role of the tumor microenvironment in contributing to the tumor suppressive effect of EZH2 inhibition." (PMID 39202398, 2024). "In MDS, the presence of mutations that inactivate EZH2 suggested that, under certain cell conditions, EZH2 may act as a tumor suppressor." (PMID 39655332, 2024). "Patients whose tumors had greater than 10% or more tumor cells with positive nuclear staining for EZH2 had worse recurrence-free survival rates than did those with lower than 10% positively stained tumor cells, which is consistent with what has been observed by others." (PMID 38886296, 2024). "Additionally, the tumor-suppressive functions of EZH2 are to maintain repression of a small number of oncogenes, including pleiomorphic adenoma gene 1 (Plag1) and potentially Lin28b, which, upon derepression, will accelerate the development of AML." (PMID 39655332, 2024). "In addition, EZH2 inactivation enhances T cell recruitment to tumor regions by promoting naïve CD4+ T cells to differentiate into effector Th cells." (PMID 39768352, 2024).
tumor (continued). "In addition, tumor-associated macrophages (TAMs) secrete the IL-6 cytokine, which triggers PRMT1 to mediate the formation of asymmetric dimethylation of the oncogene EZH2 at arginine 342, reinforcing EZH2 stability and leading to BC metastasis." (PMID 39201539, 2024). "However, the superior efficacy of integrin α11 siRNA therapy over EZH2 siRNA treatment was demonstrated by enhanced inhibition of tumour growth and prolonged survival in murine models bearing tumours." (PMID 38664825, 2024). "Importantly, a combination of EZH2 inhibitors with anti‐PD‐1 immune checkpoint blockade therapy improves the tumor microenvironment, enhances sensitivity to immunotherapy, and exerts synergistic anticancer effects." (PMID 38520088, 2024). "Ongoing studies highlighted the impact of EZH2 in tumor cells on TAMs via H3K27 methylation." (PMID 38534385, 2024). "Thus, the use of EZH2 inhibitors in vivo suppressed tumor growth, whereas TRM production and tumor immunity were inhibited at the same time, ultimately leading to the loss of tumor suppression." (PMID 38243324, 2024). "This suggests that a high level of EZH2 expression is widely detectable in tumor tissue." (PMID 40135141, 2024). "EZH2 inhibitors upregulate PD‐L1 expression in tumor tissue, which may be one of the reasons limiting the efficacy of EZH2 inhibitors in solid tumors." (PMID 38520088, 2024). "In tumor cells, miRNAs interacting with EZH2 contribute to macrophage polarization." (PMID 38534385, 2024). "To understand whether neutrophils were also altered in the bone marrow when an EZH2 inhibitor was administered, we performed scRNA-seq on the bone marrow of the same mice used for the tumor analysis." (PMID 38265267, 2024). "EZH2, being an epigenetic modulator, also has an effect on the tumor microenvironment." (PMID 38893092, 2024). "Additionally, the oncogene EZH2 upregulates the downregulation of miRNA‐101, which in turn downregulates rap1GAP, another tumor suppressor gene, encouraging head and neck malignancies." (PMID 38522008, 2024). "Additionally, miR-101-3p exhibited targeting capabilities towards EZH2 (histone methyltransferase), enhancing its suppressive impact on tumor growth." (PMID 38730633, 2024). "However, the critical role of EZH2 in TRM differentiation restricts the anti-tumor effects of EZH2 inhibitor in vivo." (PMID 38243324, 2024). "In addition, small-molecule EZH2 inhibitors eliminate tumor cell growth in diffuse intrinsic pontine glioma through a mechanism induced by the tumor suppressor protein, p16INK4A." (PMID 38225241, 2024). "Notably, in a clinical study involving 696 patients, high EZH2 levels were positively correlated with increased tumor cell proliferation in four major cancer types including cutaneous melanoma and cancers of the endometrium, prostate, and breast." (PMID 38473229, 2024). "Interestingly, miR-101-3p engages with EZH2, impeding RB tumor cell formation, while the inhibition of EZH2 through specific inhibitors displays therapeutic potential against RB by inhibiting proliferation and metastasis." (PMID 38920989, 2024). "In addition, MELK knockdown or downregulated EZH2 reduced the weight and volume of subcutaneous tumours of nude mice." (PMID 38652219, 2024). "Our in vivo findings are consistent with previous studies demonstrating that cells with high EZH2 expressions have an advantage in metastasizing, while EZH2 KO 4T1 tumor-bearing mice have significantly longer survival and decreased occurrence of metastatic colonies." (PMID 38791429, 2024). "Finally, H&E staining of mouse brain tissue confirmed tumor location, followed by IHC staining, which demonstrated significantly lower EZH2 expression and significantly higher KCC2 expression in the treatment group compared to the other two groups." (PMID 38886655, 2024). "The regulation of EZH2 has considerable therapeutic potential, as the depletion of EZH2 may aid in tumor suppression." (PMID 39768352, 2024).
tumor (continued). "Furthermore, utilizing publicly available single-cell datasets, we demonstrated that EZH2 is predominantly expressed in tumor cell populations." (PMID 38886655, 2024). "Inhibition of EZH2 can boost tumor immunotherapy through various mechanisms." (PMID 39620228, 2024). "The Myc/EZH2 axis plays a critical role in promoting tumor growth in oncoviruses." (PMID 38534385, 2024). "The cumulative effects of these functions make EZH2 an attractive target for tumor therapy." (PMID 39640777, 2024). "EZH2 is considered an upregulated oncogene in numerous cancers, leading to increasing H3K27me3 to repress senescence- and migration-related genes to suppress tumor growth." (PMID 38646788, 2024). "Our results indicated that PROTAC EZH2 degrader-1 could overcome resistance by inhibiting EZH2 and suppressing tumour growth, which contradicts previous reports showing that EZH2 is responsible for drug resistance in SCLC." (PMID 38644473, 2024). "Furthermore, we explored the oncogenic role of HOTAIR through cell experiments and found that it potentiates cancer metastasis and tumor progression by recruiting EZH2." (PMID 38696320, 2024). "Additionally, histone methyltransferase enhancer of EZH2 can activate methylation of lysine 27 on histone H3 within nucleosomes, promoting cell proliferation and suppressing transcription of tumor suppressor genes in both conditions." (PMID 39445058, 2024). "Numerous drugs aimed at these mutations have demonstrated encouraging outcomes in preclinical tumor models and clinical advancements include FDA-approved EZH2 inhibitors for cancers with SMARCB1 mutations and more targets are now identified through genome-wide screens for clinical trials." (PMID 39348027, 2024). "Further research, for defining clear cut-off values and analysis of various EZH2-intensity between primary tumor tissue, tumor relapse tissue and distant metastasis would be of clinical interest and could benefit in the future." (PMID 40135141, 2024). "EZH2 is known to regulate genes involved in E/M plasticity, and thus EZH2 may contribute to the differences in E/M phenotypes observed in cancer cells as a function of location within the tumor." (PMID 39409910, 2024). "In malignant tumor models, EZH2 is key in promoting tumor growth and metastasis." (PMID 39565059, 2024). "A CRISPRko screen conducted in the rhabdoid tumor cells G401 and G402 in presence of the enhancer of zeste homolog 2 (EZH2) inhibitor GSK126 revealed that the H3K36me2 methyltransferase nuclear receptor binding SET domain protein (NSD) 1 was connected with resistance." (PMID 38255778, 2024). "Consequently, EZH2 ablation or pharmacological inhibition is often deemed effective in curbing tumor growth and enhancing immune activity within the TME." (PMID 39080807, 2024). "Besides, EZH2 and G9a have been shown to functionally cooperate in gene silencing in ES cells and in the induction of tumor cell death." (PMID 38167468, 2024). "Thus, EZH2 is key to 4T1 aggressiveness as its tumor-intrinsic knockout alters their in vitro secretome and in vivo primary tumor growth, TIN/TIL poise, and metastasis." (PMID 38791429, 2024). "In summary, although EZH2 is a well-established marker of tumor aggressivity, our results suggest that its expression is decreased and its prognostic role might be marginal in young HNSCC patients." (PMID 38791289, 2024). "Interestingly, EZH2 has demonstrated a potential tumor-suppressive role in subsets of diffuse midline gliomas by inducing oxidative phosphorylation." (PMID 38183103, 2024). "Still, we recommend further analysis for determination a viable cut-off value and further research on the correlations of EZH2 with tumor type, location, progress, and its therapeutic response, before EZH2 diagnostics and therapy makes the transition to routine hospital practice." (PMID 40135141, 2024).
tumor (continued). "In addition, chemotherapy activated the EZH2/STAT3 pathway in tumor cells, resulting in elevated levels of miR-378a-3p and miR-378d in cells and exosomes." (PMID 39372872, 2024). "Notably, under CDDP treatment, the combined application of the SIRT7 shRNA and EZH2 shRNA lentiviruses markedly enhanced the tumor RND3 protein levels compared to the administration of either shRNA lentivirus alone." (PMID 39719443, 2024). "EZH2 was highly expressed in tumor samples but poorly expressed in normal tissue samples." (PMID 39640777, 2024). "Additionally, the absence of in vivo validation experiments to illustrate that EZH2 facilitates tumor metastasis through epigenetic regulation of CCL22-CCR4 expression represents a limitation of this study." (PMID 39513112, 2024). "Novel studies have reported more aggressive oral SCCs after EZH2-knockdown in a mouse model and discussed the tumor suppressor role of EZH2, concluding that EZH2-expression may differ even in the same cancer entity depending on the stage of disease." (PMID 40135141, 2024). "Thus, EZH2 indirectly promotes the buildup of HIF-1α, which causes tumor cells to dedifferentiate by blocking PHD3." (PMID 38911968, 2024). "In addition, EZH2 activity is significantly lower in normal cells than in tumor cells and is particularly important during embryonic development." (PMID 38254784, 2024). "In addition, GSK-126, an EZH2 inhibitor, also suppressed the tumor growth less strongly than gene KD." (PMID 38664825, 2024). "Although the bulk tumor cell mass was effectively killed by dual EZH2/CDK4/6 blockade, our flow cytometric approach may have missed or unidentified potential effects on this rare subpopulation." (PMID 39054369, 2024). "Moreover, EZH2 inhibition can enhance the expression of neoantigens, further promoting an anti-tumor immune response." (PMID 39335494, 2024). "Therefore, assessing EZH2 expression levels can help further differentiate the malignancy of tumor cells under hypoxic conditions from the perspective of immune infiltration." (PMID 38911968, 2024). "EZH2 plays two key roles in regulating the immune response within tumor cells." (PMID 38534385, 2024). "Through a combination of specific antibodies for the tumor cell marker Ezh2, the pan B-cell marker B220/CD45R, and the neutrophil marker Ly6g, a significant decrease of splenic B-cells with a concomitant increase in Ly6g+ myeloid cell infiltration in tumors was revealed." (PMID 39362842, 2024). "Importantly, EZH2 plays a critical role in tumor progression and metastasis and is aberrantly expressed in different malignancies." (PMID 39550391, 2024). "This study suggests that high EZH2 levels can be used as a predictive factor to identify increased tumor cell proliferation and aggressive subgroups in several cancers, and that it may be used as target for the development of therapies." (PMID 38473229, 2024). "Interestingly, we and others have recently found EZH2 to be overexpressed in tumors with loss of BAP1 function, thereby altering the chromatin distribution of PRC1 and PRC2 complexes and leading to a dependency on EZH2 for these tumor cells." (PMID 38054839, 2024). "Silencing MELK or EZH2 or overexpressing LATS2 suppressed tumour formation in nude mice." (PMID 38652219, 2024). "It’s important for future research to investigate the typical duration required for EZH2 levels to normalize after surgery, as this could help monitor tumor recurrence." (PMID 38476362, 2024). "Last but not least, EZH2 has been reported to increase the recruitment of tumor-associated macrophages (TAMs) by cancer cells overexpressing it." (PMID 39769907, 2024). "The X-escapee KDM6A opposes EZH2 function and can act as a tumor suppressor." (PMID 38949020, 2024).
tumor (continued). "However, caution with these agents is warranted, as EZH2 was recently demonstrated to play a tumor-suppressive role in DMG pathogenesis." (PMID 38994974, 2024). "In light of the observation that a high EZH2-score-I and -II correlated with tumor variables, we postulated that a comparable situation might be at play with regard to the final score model." (PMID 40135141, 2024). "Furthermore, the concurrent administration of the shRNA SIRT7 and shRNA EZH2 lentiviruses resulted in the most significant enhancement in the CDDP treatment-induced tumor tissue weight reduction." (PMID 39719443, 2024). "This also suggests that, although this study primarily focuses on the enhanced effects of EZH2 inhibition on tumor cell immune checkpoints, targeting EZH2 in vivo can lead to more complex and dynamic effects, which still require further exploration in the future." (PMID 38520088, 2024). "Notably, EZH2 activation was observed in SNUC tumor cells, indicating its crucial role in the carcinogenesis of SNUC." (PMID 39565059, 2024). "Consequently, EZH2 has emerged as a prominent target for tumor treatment, with several EZH2 inhibitors already being applied in clinical practice." (PMID 39043634, 2024). "Nevertheless, our study revealed that most tumor samples exhibited an EZH2 expression of > 50%." (PMID 40135141, 2024). "In the context of GBM, HCMV-GBM strains isolated from GBM biopsies induced a CEGBC phenotype exhibiting upregulated EZH2 and Myc with tumor heterogeneity, proneural-to-mesenchymal plasticity, as well as stemness resulting in spheroid formation and invasiveness." (PMID 38534385, 2024). "Notably, patients with ESCC manifest significantly heightened expression of EZH2, correlating with tumor dimensions, distant metastasis, and abbreviated disease‐free survival." (PMID 39184862, 2024). "In cancer, EZH2 overexpression has been identified in various tumor types, acting as an oncogene." (PMID 39456545, 2024). "Analyzing the role of EZH2 in various tumor types is therefore clinically relevant." (PMID 40135141, 2024). "The inhibition of EZH2 could increase the immunogenicity of tumor cells by redefining cellular epigenetic structure and favoring the expression of genes, coding for both the presentation of new antigens and the recruitment of antitumor immune cells." (PMID 38893092, 2024). "In addition to strongly influencing the tumor immune microenvironment, EZH2 inhibition drove dramatic increases in expression of both MHCI and MHCII in vitro." (PMID 38265267, 2024). "By developing a two-site tumor system model, a study found that liver metastasis can inhibit systemic anti-tumor immune response, and proposed that CTLA-4 inhibitors or enhancer of zeste homolog 2 (EZH2) inhibitors combined with PD-1 inhibitors can restore systemic anti-tumor immune activity." (PMID 39493446, 2024). "Inhibiting EZH2 using DZNep or EPZ can turn the tumor from cold to hot by activating the dsRNA/STING/IFN axis or downregulating the expression of protumor inflammatory cytokine G-CSF, resulting in upregulation of activated CD8+ T cells and downregulation of immunosuppressive neutrophils." (PMID 39133578, 2024). "Loss of EZH2 did reduce recruitment of inflammatory cells and, when combined with a more aggressive PDAC model, promoted widespread PDAC progression and remodeling of the tumor microenvironment." (PMID 39739419, 2024). "While our in vitro studies indicate that EZH2 inhibition and IFNγ are both required for MHCII upregulation, in vivo the changes seen in the tumor cells may be secondary to immune modulation by EZH2 inhibition." (PMID 38265267, 2024). "Targeting EZH2 inhibited HNSCC tumor growth and induced cell apoptosis in vivo." (PMID 40135141, 2024). "The anti-tumor effects of EZH2 inhibition may be through downregulation of cell-cycle related genes in PRAD and other AR-low NEPC-transitioning models, potentially collaborating with its impact on AR signaling." (PMID 38405800, 2024).